ITGA2 (integrin subunit alpha 2)
Diseases named in the same sentence as ITGA2 in open-access papers (continued):
Sharing a sentence is not in itself a finding about the gene and the disease.
cancer (continued). "The presence of genomic instability disorder is a notable feature of cancer, and compelling evidence indicates a correlation between ITGA2 and genomic instability in PDAC." (PMID 39568561, 2024). "In normal tissues and organs, the expression of ITGA2 remains very low; however, its overexpression has been identified in multiple cancer types, including HCC42." (PMID 38553531, 2024). "Considering its role as a facilitator of cancer progression in gastrointestinal tumors, it is plausible that ITGA2 hampers the immune cells’ antitumor capabilities within the TME by modulating their mobility and immune checkpoints." (PMID 39568561, 2024). "Further investigation is warranted to ascertain ITGA2’s potential as a novel immunotherapeutic target for malignant tumors." (PMID 39568561, 2024). "Taken together, targeting the ITGA2-mediated interaction between cancer cells and collagen emerges as a promising therapeutic approach for mitigating the risk of cancer metastasis and dissemination." (PMID 39568561, 2024). "The up-regulation of ITGA2 facilitates the migration and proliferation of cancer cells by augmenting the adhesion of CRC cells to collagen and laminin." (PMID 39568561, 2024). "LINC00355 was shown to promote invasion and migration in cancer cells and xenograft animals by regulating the transcription of three downstream genes (ITGA2, RAD18, and UBE3C) and participating in six ceRNA axes." (PMID 38125763, 2023). "An increase in matrix stiffness prompted cancer cells to express more ITGA2 and become chemoresistant." (PMID 36765586, 2023). "The relationship between ITGA2 and cancer has attracted significant research attention in recent years." (PMID 37881431, 2023). "It has recently been reported that ITGA2 promotes the invasion of malignant tumors by activating the STAT3 signaling pathway and subsequently upregulating PD-L1 expression." (PMID 37377917, 2023). "It has been reported in the literature that ITGA2 plays a critical role in cancer cell progression and the regulation of PD-L1 by activating the STAT3 pathway." (PMID 35794161, 2022). "In another study, the authors reported that ITGA2 increased the PD-L1 expression in multiple types of cancer cells and improved the antitumor efficacy of immune therapy." (PMID 35936750, 2022). "ITGA2 has been targeted by small molecules and antibodies as potential cancer therapies and is in clinical trials." (PMID 35936750, 2022). "ITGA2 is overexpressed in many cancers such as hepatocellular carcinoma, ovarian cancer, and pancreatic ductal adenocarcinoma, and is thought to be related to cell adhesion and cell surface-mediated signal transduction." (PMID 35193647, 2022). "Consistently, the gene expression of collagen I receptors, linked to active tissue remodeling and cancer, including DDR2, ITGA2, ITGA10, ITGA11 and ITGB1 was higher in OS compared to RMS, whilst DDR1 expression was higher in RMS tumors." (PMID 35957513, 2022). "Our data, along with the role of ITGA2 in other cancers, suggest that ITGA2 signaling can be a potential molecular target for therapeutic development and a predictive biomarker for iCCA progression." (PMID 36575207, 2022). "The pharmacological inhibition of ITGA2 counteracts the cancer-promoting microenvironment and ameliorates pancreatic lesions in vivo." (PMID 35719923, 2022). "Increased expression levels of HLF, shown to promote cell-cycle progression in various cancers, ITGA2, MUC1, and DPY19L1 have also been proposed to confer prognostic value for the survival of patients suffering from LUAD malignancies." (PMID 36551790, 2022). "Integrin α2 (ITGA2) triggers cancer cell adhesion to collagen, promotes cell migration, anoikis resistance, mesothelial clearance, and peritoneal metastasis." (PMID 35894206, 2022). "ITGA2 mediated adhesion to type I collagen and are expressed on cancer cells, immune cells, stroma cells, and endothelial cells." (PMID 35936750, 2022).
cancer (continued). "The abnormal expression of ITGA2 has been correlated with unfavorable prognoses in multiple types of cancer." (PMID 35936750, 2022). "Recently, three research groups have identified ITGA2 as a potential therapeutic target for treating pancreatic cancer, another cancer type that shares the characteristic of desmoplastic stroma high in collagen type I49,50." (PMID 36575207, 2022). "For instance, the integrin subunit ITGA2 was previously shown to promote cancer cell proliferation, invasion, and drug resistance by activating AKT signaling pathways." (PMID 34332611, 2021). "In previous studies, some experts have already investigated a new mechanism by which ITGA2 plays a key role in regulating cancer immune response." (PMID 34778054, 2021). "Integrin subunit α2 (ITGA2) is an oncogene factor which promotes metastasis and growth ability of cancer cells and it is thought to reduce sensitivity of cancer cells of PTX through activation of Akt/FoxO1 signaling pathway." (PMID 33644048, 2021). "Growing evidence indicates that ITGA2 participates in the process of cancer pathogenesis and development." (PMID 34778054, 2021). "Integrin alpha 2 (ITGA2) promotes cancer metastasis through selective adhesion to ECM proteins; however, the specific contribution of integrin glycosylation remains uncertain." (PMID 34646995, 2021). "Briefly, the C-terminal fused HA tagged-ITGA2 mutants was built on a lentiviral-based bicistronic vector and transduced into previously established ΔITGA2 cancer cells." (PMID 34646995, 2021). "Despite its crucial role in cancer, this is the first report highlighting ITGA2 methylation as potential biomarker for cancer prognosis." (PMID 34944974, 2021). "We found that the cancer-related indicators were more enriched in the LGG subgroup with high ITGA2 expression compared with the subgroup of low expression." (PMID 34778054, 2021). "We provide for the first time a detailed map of human ITGA2 glycosylation derived from cancer cells." (PMID 34646995, 2021). "Our histopathological evidence has shown that COL12A1 and FN1 are expressed from stromal cells, THBS2, and VCAN from stromal and cancer cells, while ITGA2, LAMB3, and LAMC2 are expressed solely from the cancer cells." (PMID 34007003, 2021). "(G) Representative fluorescence images with membranous ITGA2 expression in WT and ΔITGA2 cancer spheroids collected from ultra-low attachment plate." (PMID 33026975, 2020). "The ITGA2 gene codes for integrin subunit α2 and is known to participate in the proliferation, invasion, and metastasis of cancer cells." (PMID 32202508, 2020). "Vice versa, constitutive overexpression of ITGA2 in ITGA2low cancer cell line (n = 4) significantly enhanced cell adhesion to collagen I and IV (p<0.001) indicating a cell line-independent binding specificity of ITGA2 to collagen I, III, and IV." (PMID 33026975, 2020). "The ITGA2 gene, which codes for integrin subunit α2, is involved in the proliferation, invasion, and metastasis of cancer cells." (PMID 32202508, 2020). "Overall, we describe the critical contribution of collagens elevated in the premetastatic niche and the mechanism of how ITGA2-mediated cancer cell dissemination during peritoneal metastasis." (PMID 33026975, 2020). "It is well known that ITGA2, as an oncogene, participates in biological processes of cancers, such as progression, invasion, metastasis and angiogenesis." (PMID 32557953, 2020). "ITGA2 forms a homodimer with ITGB1, and dysregulated levels of ITGA2/ITGB1 can mediate the signal pathways that enhance malignant transformation in multiple types of cancer cells." (PMID 32899691, 2020). "Using multiple gene-edited cell lines and patient-derived samples, we demonstrate that ITGA2 triggers cancer cell adhesion to collagen, promotes cell migration, anoikis resistance, mesothelial clearance, and peritoneal metastasis in vitro and in vivo." (PMID 33026975, 2020).
cancer (continued). "Taken together, our findings suggest that ITGA2 is essential in mediating the initial cancer cell-collagen adhesion, a key step for peritoneal dissemination." (PMID 33026975, 2020). "Mechanistically, we have identified that ITGA2-collagen interaction fosters cancer cell survival, cell migration, and anoikis resistance through the FAK/MAPK signaling axis." (PMID 33026975, 2020). "We acknowledge that this is a limitation of our study which directly influences the conclusions that we can logically make in regard to the importance of ITGA2/B1 in cancer progression." (PMID 33276802, 2020). "Overexpression of ITGA2 increases cell proliferation and invasiveness of cancer cells by activation of the PD-L1/STAT3 axis." (PMID 32824235, 2020). "Here, we performed a quantitative and unbiased screening of 70 cancer-related antigens using comparative flow cytometry and, for the first time, identified integrin alpha-2 (ITGA2) as a novel molecular target for GBM." (PMID 30996239, 2019). "Since up-regulated ITGA2 was a poor prognostic biomarker for cancer, we explored its biological role in cancerous tumors further." (PMID 31818309, 2019). "Per all these results, ITGA2 transcriptionally regulates PD-L1 expression in various types of cancer cells." (PMID 31818309, 2019). "We identified a novel mechanism by which ITGA2 plays a critical role in modulating cancer immune response by transcriptionally increasing the expression of PD-L1 in cancer cells." (PMID 31818309, 2019). "Meanwhile, we also found that ITGA2 transcriptionally increased PD-L1 expression in multiple types of cancer cells." (PMID 31818309, 2019). "By carrying out a drug sensitivity assay and several verification experiments, we determined that ITGA2 bound with STAT3 to initiate the transcription of PD-L1 by increasing the phosphorylation level of STAT3 in cancer cells." (PMID 31818309, 2019). "Per the immunoprecipitation assay (IP), ITGA2 interacted with STAT3 in various types of cancer cells." (PMID 31818309, 2019). "The pathway analysis of the 40 most significantly regulated genes indicated that ITGA2 repression occurred in the PD-1 checkpoint pathway in cancer cells." (PMID 31818309, 2019). "Our results suggest that ITGA2 plays a critical role in cancer cell progression and the regulation of PD-L1 by activating the STAT3 pathway." (PMID 31818309, 2019). "All our findings suggest that more research has to be carried out on the use of ITGA2 as a novel immune therapeutic target for malignant tumors." (PMID 31818309, 2019). "Blocking ITGA2 inhibited the proliferation and invasion ability of cancer cells significantly, whereas overexpressed ITGA2 increased the degree of those processes considerably." (PMID 31818309, 2019). "Functional assays, such as the MTS assay, colony formation assay, and transwell assay, were used to determine the biological role of ITGA2 in human cancer." (PMID 31818309, 2019). "Following the knockdown of ITGA2 using short Harpine RNA (shRNA) in PANC-1, HepG2, SGC-7901, and MDA-MB-231 cell lines a,b, the MTS and colony formation assays demonstrated that silencing ITGA2 inhibited the cancer cell growth c,d." (PMID 31818309, 2019). "The extents of antibody-mediated cancer inhibition positively correlated with the expression levels of the ITGA2." (PMID 29743821, 2018). "The extents of inhibition positively correlated to the expression of ITGA2 as the anti-cancer effects were more pronounced in ITGA2-overexpressing cells." (PMID 29743821, 2018). "The regulatory network analysis showed the association of some important hub proteins like GSK3B, NUMB, PEG3, ITGA2 and DLG2 with cancer-associated pathways." (PMID 28587194, 2017). "In the early process of cancer metastasis, ITGA2 reduction helps cancer cells to detach the primary cancer; in late phase cancer, ITGA2 recovery helps cancer cells to locate in lymph node and distant organs." (PMID 26258411, 2015).
cancer (continued). "However, the molecular mechanism of ITGA2 loss in primary cancers remains unclear." (PMID 26258411, 2015). "Collectively, our data showed that down-regulation of ITGA2 by miR-373 induces cancer cell migration by detaching the cell-cell adhesion and regulating deploymerization of cytoskeleton." (PMID 26258411, 2015). "However, the molecular mechanism of ITGA2 loss in cancer cells is still unknown." (PMID 26258411, 2015). "Silencing of ITGA2 detached cell-cell interactions, induced the deploymerization of stress fiber F-actin and stimulated cancer cell migration, similar to the effect of miR-373 over-expression." (PMID 26258411, 2015). "In addition to the role of ITGA2 in cancer progression, there are studies demonstrating its role in mediating resistance." (PMID 41008552, 2025). "Another cancer-associated module, the adhesion cluster, shows conceptual similarity to the μ-21-specific corresponding cluster, though only three integrin family proteins (ITGA1, ITGA2, ITGAV) are shared between them." (PMID 41373892, 2025). "Anoikis resistance, essential for cancer metastasis, is promoted in cancer stem cells (CSCs) by elevated ITGA2 and ITGB1 expression, which interact with EGFR to activate the ERK/Akt survival pathway, enabling CSCs to evade cell death in the absence of extracellular matrix." (PMID 41008552, 2025). "In parallel with our findings, several studies have highlighted the role of integrins, particularly ITGA2, in cancer progression, and have also demonstrated that integrin inhibition may enhance therapeutic efficacy." (PMID 41008552, 2025). "Moreover, the secretion of TGF-α by CRC cells enhances the expression of ITGA2, leading to increased cell adhesion to type IV collagen and promoting the metastasis and dissemination of cancer cells." (PMID 39568561, 2024). "Hence, we primarily focus on elucidating the biological function and mechanism of ITGA2 within the digestive tumor microenvironment, while highlighting its prospective utilization as a therapeutic target for cancer therapy." (PMID 39568561, 2024). "In cancer tissues, the expression of ITGA2 was observed to have varying levels: weak expression was present in 25.8% (16/62) of cases, moderate intensity expression was found in 22.6% (14/62) of cases, and high expression was detected in 51.6% (32/62) of cases." (PMID 37881431, 2023). "Finally, we reported that overexpression of ITGA2 in gemcitabine-sensitive cells (MiaPaCa-2) induces chemoresistance and cancer cell growth both in vitro and in vivo." (PMID 36765586, 2023). "Furthermore, the transwell assay revealed a significant decrease in migration and invasion abilities of cancer cells upon down-regulation of ITGA2." (PMID 37881431, 2023). "Integrin alpha 2 (ITGA2), an extracellular matrix receptor for laminin, collagen, fibronectin, and E-cadherin, plays a role in promoting cell proliferation and invasion in different types of cancer." (PMID 37628788, 2023). "Furthermore, the high expression in several carcinoma cells of epithelial origin indicates that ITGA2 is an important key pathway in cancer pathogenesis." (PMID 35936750, 2022). "Therefore, we differentiated PDEs from TEVs using the candidate cancer surface markers ITGA2, ITGAV, and GPC1." (PMID 34948417, 2021). "Our generated glycoproteomic profile of ITGA2 from cancer cells may be useful to serve as a MS-library for identification of certain glycopeptide signatures in clinically relevant samples in future." (PMID 34646995, 2021). "However, the mutation in the α-I domain (N3NQ) and even more pronounced 10NQ, reduced ITGA2 expression on the surface of cancer cells." (PMID 34646995, 2021). "These details suggested that targeting ITGA2 may be an effective approach to improve the curative effect of cancer checkpoint immunotherapy." (PMID 34778054, 2021).
cancer (continued). "Taken together, our findings support the hypothesis that apart from overall site-specific N-glycosylation, α2-6 sialylation participates in facilitating ITGA2-dependent cancer cell survival." (PMID 34646995, 2021). "We found that ITGA2 may be interrelated to the immune response mechanism of cancer cells and was interrelated with TME." (PMID 34778054, 2021). "It is reported that the abnormal expression of ITGA2 is involved in many cancers." (PMID 34778054, 2021). "Consistent with our previous finding, loss of ITGA2 completely abolished cancer cell adhesion to collagen type I and III but not fibronectin." (PMID 34646995, 2021). "The re-overexpression of glycosylated-ITGA2 showed enhanced cell migration and invasion capability compared to KO and mutant 10NQ cells, suggesting that ITGA2-specific N-glycosylation may be involved in cancer cell-adherence to distant sites." (PMID 34646995, 2021). "ITGA2 affects cell proliferation, invasion, metastasis and angiogenesis in cancer." (PMID 34094925, 2021). "To identify whether ITGA2 facilitates cancer cell adhesion to mesothelial cells, we performed a co-culture in vitro competition adhesion assay." (PMID 33026975, 2020). "Growing evidence indicates that ITGA2/B1 can be a key pathway in cancer pathogenesis." (PMID 33276802, 2020). "Similarly, ITGA2 knockdown assays showed that cancer cell migration and invasive abilities were significantly suppressed in the SW1990 cells." (PMID 32899691, 2020). "ITGA2 inhibitor selectively blocks ATCs and cancer cell adhesion to collagen." (PMID 33026975, 2020). "Furthermore, we evaluated cancer spheroid-mediated mesothelial clearance activity of different cell lines including WT, ΔITGA2 (n = 4), and ITGA2-OE cells (n = 4)." (PMID 33026975, 2020). "The ratio of cancer cell adhesion to mesothelial cells was significantly increased for 12 and 24 hr incubation (1.92- to 2.59-fold; WT/ ΔITGA2 cells), supporting the role of ITGA2 in facilitating mesothelial cell adhesion." (PMID 33026975, 2020). "TC-I-15 specifically blocks ITGA2-collagen interaction may therefore impede cancer cells dissemination to the collagen-rich omentum." (PMID 33026975, 2020). "Here, we demonstrated that ITGA2 might regulate cancer cell proliferation and migration by regulating the expression of PD-L1." (PMID 31818309, 2019). "Therefore, our data suggest that the level of ITGA2 in cancer specimens has a positive correlation with PD-L1 expression." (PMID 31818309, 2019). "Moreover, we demonstrated that ITGA2 played an essential role in promoting cell proliferation and invasion in cancer." (PMID 31818309, 2019). "Additionally, the transwell assay showed that the migration and invasion abilities of cancer cells decreased markedly after ITGA2 down-regulation." (PMID 31818309, 2019). "Also, the expression of PD-L1 was up-regulated at both the mRNA and protein levels in cancer cells with overexpressed ITGA2." (PMID 31818309, 2019). "Thus, targeting ITGA2 is an effective method to enhance the efficacy of checkpoint immunotherapy against cancer." (PMID 31818309, 2019). "Interestingly,we detected drug sensitivity (IC50 values) from PANC-1 cells to some cancer-related pathway small inhibitors in the sh-Control and sh-ITGA2 groups." (PMID 31818309, 2019). "An abnormally expressed ITGA2 correlates with unfavorable prognoses in multiple types of cancer." (PMID 31818309, 2019). "Moreover, the transwell assay showed that migration and invasion abilities were also up-regulated in ITGA2-overexpressing cancer cells." (PMID 31818309, 2019). "Previous studies showed that blocking of ITGA2 inhibited cancer cell aggressiveness." (PMID 29988949, 2018). "Targeting ITGA2 could represent a promising strategy for cancer treatment." (PMID 37881431, 2023).